VSNL1 (visinin like 1)
Description:
Regulates (in vitro) the inhibition of rhodopsin phosphorylation in a calcium-dependent manner.
Synonyms: VILIP; HLP3; HPCAL3; HUVISL1; VILIP-1
Tractability: PROTAC: its protein half-life has been measured.
Gene: Protein-coding gene on chromosome 2 (17,539,020 to 17,657,018, forward strand). Ensembl gene ENSG00000163032.
Subcellular location (Human Protein Atlas): Cytosol
Gene Ontology:
Molecular function: protein binding; calcium ion binding
Biological process: regulation of signal transduction
Cellular component: cytosol; membrane
Genetic constraint (gnomAD): Loss-of-function variants: 6 observed, 20.97 expected, observed/expected ratio (o/e) 0.29, 90% interval 0.16 to 0.56. The upper end of that interval is the gene's LOEUF score, 0.56, which puts it in group 2 of 6, group 1 being the genes least tolerant of losing a copy. Missense variants: 100 observed, 247.33 expected, observed/expected ratio (o/e) 0.4, 90% interval 0.34 to 0.48. Synonymous variants: 93 observed, 92.01 expected, observed/expected ratio (o/e) 1.01, 90% interval 0.85 to 1.2.
Homologues: Orthologues: chimpanzee VSNL1 (100% identical), dog VSNL1 (100% identical), guinea pig VSNL1 (100% identical), macaque VSNL1 (100% identical), mouse Vsnl1 (100% identical), rabbit VSNL1 (100% identical), rat Vsnl1 (100% identical), tropical clawed frog vsnl1 (99% identical), zebrafish vsnl1b (97% identical), zebrafish vsnl1a (96% identical), pig VSNL1 (94% identical), Caenorhabditis elegans ncs-2 (46% identical), and 3 more. Paralogues in human: HPCAL4 (90% identical), HPCAL1 (68% identical), NCALD (68% identical), HPCA (66% identical), NCS1 (57% identical), RCVRN (44% identical), KCNIP4 (43% identical), KCNIP1 (42% identical), KCNIP2 (42% identical), GUCA1B (41% identical), GUCA1A (39% identical), KCNIP3 (38% identical), and 2 more.
Diseases named in the same sentence as VSNL1 in open-access papers:
VSNL1 is named in the same sentence as 76 diseases in open-access papers, as found by Europe PMC text mining. Sharing a sentence is not in itself a finding about the gene and the disease. The quoted sentences say what the papers report.
Alzheimer disease (23 papers, 2010 to 2025). A progressive, neurodegenerative disease characterized by loss of function and death of nerve cells in several areas of the brain leading to loss of cognitive function such as memory and language. "The visinin-like 1 (VSNL1) gene encodes visinin-like protein 1, a peripheral biomarker for Alzheimer disease (AD)." (PMID 25806004, 2015). "We found that Vsnl1, which is located on mouse chromosome 12, has been implicated in Alzheimer’s disease." (PMID 24090483, 2013). "Novel candidates are associated with neurodegenerative disorders including Alzheimer's disease (VSNL1), prion disease (SCRG1, HSPH1, HSPA5 and CTR9) and age-related degeneration (GAS6 and GNG11)." (PMID 21569303, 2011). "Moreover, top hub genes in this module were associated with the development of Alzheimer’s disease, including VSNL1, INA, CHN1, NMNAT2, and MAP7D2." (PMID 37284017, 2023). "The research concerning VSNL1 has mainly focused on neurological diseases such as Alzheimer’s disease and medulloblastoma." (PMID 36979826, 2023). "Despite having only one GO term, Vsnl1 has been identified as a biomarker of Alzheimer disease in cerebrospinal fluid." (PMID 28190221, 2017).
cognitive decline (18 papers, 2013 to 2025). "Overlapping the proteins consistent in both AD datasets with data from transgenic mice revealed four novel, high-confidence candidates that were associated with cognitive decline and drug-mediated multi-target kinase inhibition: PACSIN1, GJA1, VSNL1 and NDUFB5." (PMID 33530349, 2021).
neuroblastoma (6 papers, 2008 to 2023). Neuroblastoma (NB) is the most common solid, extracranial childhood tumor. "Regarding the role of VSNL1 in apoptosis, forced VSNL1 expression in a subclone of SK‐N‐AS neuroblastoma cells with low invasive ability led to the suppression of detachment‐induced apoptosis." (PMID 37096864, 2023). "VSNL1 was also found to be overexpressed in neuroblastoma specimens from patients with distant metastases." (PMID 33376484, 2020). "Upregulation of VSNL1 potentiated the anoikis-resistant ability of neuroblastoma tumor cells and enhanced neuroblastoma cell invasiveness and metastasis." (PMID 25730906, 2015). "The participation of Vsnl1 in the regulation of proliferative and invasive properties within neuroblastoma has already been suggested." (PMID 19812696, 2009). "VSNL1 was significantly highly expressed in highly invasive neuroblastoma cells and in gastric noncardiac adenocarcinomas by the gene expression profiles of GSE29272." (PMID 33376484, 2020).
schizophrenia (6 papers, 2012 to 2023). A major psychotic disorder characterized by abnormalities in the perception or expression of reality. "Other studies have recently found the association of single-nucleotide polymorphisms (SNPs) in the VSNL1 gene with neurological disorders like schizophrenia." (PMID 27356971, 2016). "Although the focus of our study was on risk for AD, genetic variants in VSNL1, altered brain VSNL1 mRNA expression, and altered brain levels of Vilip1 protein have been reported in schizophrenia." (PMID 25806004, 2015). "While the full functional role of VSNL1 remains unclear, multiple studies have implicated VSNL1 in progressing calcium and synaptic dysfunction in AD, stroke and schizophrenia." (PMID 33530349, 2021). "Many of these target genes, such as RELN, DRD1, VSNL1, and HTR2A, with known function in neural connectivity, have already been associated with the development of schizophrenia." (PMID 32764320, 2020). "This was accompanied by the downregulation of miR-181b target genes with an implication in schizophrenia development, including VSNL1, a member of the visinin/recoverin subfamily of neuronal calcium sensor proteins, and the glutamate receptor GRIA2, which is involved in synaptic plasticity." (PMID 32764320, 2020). "Of particular relevance to the current report was the finding that microRNA miR-181b, which is elevated in schizophrenia, can downregulate VSNL1 expression in model systems and correlates with reduced VSNL1 expression in the superior temporal gyrus in subjects with schizophrenia." (PMID 25806004, 2015).
Stroke (6 papers, 2013 to 2024). Sudden impairment of blood flow to a part of the brain due to occlusion or rupture of an artery to the brain. "Moreover, the visinin-like protein-1 (VSNL-1) gene, a neuronal calcium sensor protein identified as a specific plasma biomarker of stroke patients, was decreased and correlated with the increase of miR-124 expression following cerebral ischemia." (PMID 31878035, 2019). "We evaluated the blood profiling of several neuro-astroglial markers, including candidate neuronal markers (VSNL-1 and Ngb) that have not been tested in human stroke patients." (PMID 23497639, 2013). "Most of the stroke patients displayed negative GFAP and VSNL-1 in the peripheral blood during this time period, indicating that these proteins are unlikely to be released from the brain to the bloodstream during this time window of stroke." (PMID 23497639, 2013).
amyotrophic lateral sclerosis (5 papers, 2018 to 2022). Amyotrophic lateral sclerosis (ALS) is a neurodegenerative disease characterized by progressive muscular paralysis reflecting degeneration of motor neurons in the primary motor cortex, corticospinal tracts, brainstem and spinal cord. "Furthermore, VSNL1 aggregates are found in amyotrophic lateral sclerosis (ALS)-associated deposits, linking them to neuronal impairment." (PMID 32311028, 2020).
colorectal cancer (5 papers, 2014 to 2024). A primary or metastatic malignant neoplasm that affects the colon or rectum. "It has been reported that down-regulation of VSNL1 inhibits the proliferation, migration, and invasion of colorectal cancer cells." (PMID 38909013, 2024). "In cancers, VSNL1 is overexpressed in various cancers such as GC, colorectal cancer, non-small cell lung cancer, and squamous cell carcinoma, and inhibits cell proliferation, adhesion, and infiltration." (PMID 35595817, 2022). "VSNL1 mRNA was also significantly highly expressed in colorectal cancer tissue with lymph node metastasis." (PMID 33376484, 2020). "VSNL1 has also been investigated in gastrointestinal tumors, where it promotes the rapid growth and metastasis of gastric cancer cells, lymph node metastasis, and the deterioration of colorectal cancer." (PMID 36979826, 2023). "Considering that some studies have shown that the high expression of VSNL1 in colorectal cancer is related to the high degree of tissue differentiation, it is speculated that the function of VSNL1 may be related to the metastasis of cholangiocarcinoma." (PMID 36979826, 2023). "Co-IP experiments indicated that VSNL1 can bind to COL10A1, which, when up-regulated, can promote colorectal cell proliferation, migration and invasion and reverse the effect of sh-VSNL1 on colorectal cancer cells." (PMID 38909013, 2024).
lymph node metastasis (5 papers, 2014 to 2024). "They observed that, compared to low VSNL-1 expression, high VSNL-1 expression was significantly associated with a high rate of lymph node metastases and poor prognosis for patients." (PMID 38909013, 2024). "Although VSNL1 is an indicator of lymph node metastasis and poor prognosis in CRC patients,44VSNL1 expression levels were not correlated with the CRC clinical stage or prognosis in the GEPIA and UALCAN databases." (PMID 37096864, 2023). "Upregulation of VSNL1 is an indicator of lymph node metastasis and poor prognosis in patients with CRC." (PMID 27013928, 2016). "Furthermore, VSNL1 expression was positively correlated with Lauren's classification, lymph node metastasis, distant metastasis, TNM stage, and prognosis." (PMID 33376484, 2020).
gastric cancer (4 papers, 2015 to 2023). A primary or metastatic malignant neoplasm involving the stomach. "The aim of this study was to investigate the role of Visinin Like 1 (VSNL1) in the proliferation and migration of gastric cancer (GC) cells as well as its clinical prognostic significance." (PMID 33376484, 2020). "Indeed, VSNL1 overexpression was associated with a higher risk of lymphatic invasion and a poorer prognosis in a series of patients with early stage CRC, and downregulation of this gene was observed in camptothecin-resistant gastric cancer cell lines." (PMID 25730906, 2015). "Few studies have examined VSNL1 expression and function in gastric cancer (GC)." (PMID 33376484, 2020).
glioma (3 papers, 2016 to 2024). A benign or malignant brain and spinal cord tumor that arises from glial cells (astrocytes, oligodendrocytes, ependymal cells). "VSNL1, the gene highly upregulated upon high SIRT5 expression in gliomas, encodes visinin-like protein 1 (VILIP-1)." (PMID 39201811, 2024). "Among the 10 candidates, high mRNA expression of CCL8, FCGR2B, and TUBA4A and low mRNA expression of GABRD, PRAME, and SYN1 were significantly correlated with worse prognosis, while the mRNA expression of CCL18, SCN1B, SNCB, and VSNL1 showed no connection to the overall survival of glioma patients." (PMID 36685974, 2022).
melanoma (3 papers, 2008 to 2025). A malignant, usually aggressive tumor composed of atypical, neoplastic melanocytes. "In the quest for potential anti-PD and anti-melanoma medications, drugs capable of targeting VSNL1, ATP6V1G2, and DNM1 were identified through screening in the DsigDB database." (PMID 40066251, 2025). "Among these, VSNL1, ATP6V1G2, and DNM1 exhibited significant downregulation in both PD patients and melanoma patients, suggests a common molecular mechanism underlying these two conditions." (PMID 40066251, 2025). "Retinoic acid was found to have binding affinity for VSNL1, ATP6V1G2, and DNM1, indicating its potential as a therapeutic agent for PD and melanoma." (PMID 40066251, 2025). "A total of 41 overlapping DEGs were identified, including VSNL1, ATP6V1G2, and DNM1, which were significantly down-regulated in both PD and melanoma patients." (PMID 40066251, 2025).
colon cancer (2 papers, 2018 to 2023). "Moreover, we noted that some of the mRNAs (ANLN, CFL2, FJX1, HHIP, PANX2, SCN3A, VSNL1 and ZIC2) were also associated with overall survival in patients with colon cancer." (PMID 29420609, 2018).
lung cancer (2 papers, 2008 to 2023). A malignant neoplasm involving the lung. "In previous studies, VSNL1 expression was frequently silenced by the methylation of its promoter region in non‐small cell lung cancers." (PMID 37096864, 2023). "Furthermore, the binding of nuclear respiratory factor 1 to the nuclear respiratory factor‐binding element located 50‐bp upstream of its transcription start site was important for VSNL1 expression in non‐small cell lung cancers." (PMID 37096864, 2023).
squamous cell carcinoma (2 papers, 2008 to 2020). A carcinoma arising from squamous epithelial cells. "VSNL1 decreases cellular adhesion and the migration/invasiveness of highly invasive mouse squamous cell carcinoma cells." (PMID 33376484, 2020). "VSNL1 is involved in epithelial-mesenchymal transition (EMT) in squamous cell carcinoma, and VSNL1 might regulate the aggressiveness of murine dermal squamous cell carcinoma cells." (PMID 33376484, 2020).
adenoma (1 paper, 2022). A neoplasm arising from the epithelium. "CYP11B, KCNJ5, VSNL1, CYP17A1 and Ki67 were detected by immunohistochemistry on formalin‐fixed paraffin‐embedded adrenal tissue (normal; n=2, adenoma; n=11, adenocarcinoma; n=7)." (PMID 36214464, 2022). "KCNJ5 and VSNL1 expression varied and was not different between adenomas and carcinomas (KCNJ5 220, versus 35,; p=0.2, VSNL1 210, versus 130,; p=0.3)." (PMID 36214464, 2022).
adrenocortical carcinoma (1 paper, 2023). "VSNL1 KD in adrenocortical carcinoma cells (NCI‐H295R) rendered them sensitive to Ca2+‐induced apoptosis." (PMID 37096864, 2023).
colon adenoma (1 paper, 2023). An adenoma that arises from the colon. "Additionally, VSNL1 expression was significantly greater in colon adenoma tissues than in normal colorectal tissues." (PMID 37096864, 2023).
colorectal adenoma (1 paper, 2023). An adenoma that arises from the colon or rectum. "Several datasets in the Oncomine database showed that the VSNL1 mRNA was upregulated in CRC cells and colorectal adenoma cells." (PMID 37096864, 2023).
depression (1 paper, 2015). "Although not among the top pathways identified, there was also a significant positive correlation of VSNL1 expression with the KEGG pathway for long-term depression in both age groups." (PMID 25806004, 2015).
dilated cardiomyopathy (1 paper, 2022). Cardiomyopathy which is characterized by dilation and contractile dysfunction of the left and right ventricles. "Second, AQP4, VSNL1, GABRA4, and GABRB1 were still among the hub genes obtained by subgroup analysis, indicating that these genes were strongly associated with dilated cardiomyopathy caused by myocarditis." (PMID 36286305, 2022).
Obesity (1 paper, 2014). Accumulation of substantial excess body fat. "From the known functions of these genes, GNAL, HELIOS, and SOX5 are directly related to adipose tissue metabolism or obesity, while SLC9A3, SPOCK3, ANXA10, MYLK, and VSNL1 may be indirectly related." (PMID 24962627, 2014).
Pancreatic Cancer (1 paper, 2022). "Of tumor-elevated proteins identified in LMD sampling, 4 additional tumor-associated proteins, COL17A1, VSNL1, LYPD3, and VCAN, were reported in the Pancreatic Cancer Database." (PMID 36266629, 2022). "Of 115 tumor-elevated proteins identified in LMD sampling, 4 additional tumor-associated proteins, COL17A1, VSNL1, LYPD3, and VCAN, were reported in the Pancreatic Cancer Database." (PMID 36266629, 2022).
psychosis (1 paper, 2015). "We reported that genetic variations in VSNL1 were associated with risk for psychosis in AD, a phenotype characterized by more rapid cognitive deterioration than seen in AD subjects without psychosis." (PMID 25806004, 2015). "However, how this normative regulation of VSNL1 by miR-181b might be changed in the presence of AD pathology and/or genetic variation in VSNL1, and in particular whether they may interact to underlie the association of VSNL1 genetic variation with psychosis in AD, is not known." (PMID 25806004, 2015).
rectal adenocarcinoma (1 paper, 2023). "The VSNL1 expression level was significantly enhanced in colon and rectal adenocarcinoma tissues." (PMID 37096864, 2023).